POLN (DNA polymerase nu)
Description:
DNA polymerase with very low fidelity that catalyzes considerable misincorporation by inserting dTTP opposite a G template, and dGTP opposite a T template. Is the least accurate of the DNA polymerase A family (i.e. POLG, POLN and POLQ). Can perform accurate translesion DNA synthesis (TLS) past a 5S-thymine glycol. Can perform efficient strand displacement past a nick or a gap and gives rise to an amount of product similar to that on non-damaged template. Has no exonuclease activity. Error-prone DNA polymerase that preferentially misincorporates dT regardless of template sequence. May play a role in TLS during interstrand cross-link (ICL) repair. May be involved in TLS when genomic replication is blocked by extremely large major groove DNA lesions. May function in the bypass of some DNA-protein and DNA-DNA cross-links. May have a role in cellular tolerance to DNA cross-linking agents. Involved in the repair of DNA cross-links and double-strand break (DSB) resistance. Participates in FANCD2-mediated repair. Forms a complex with HELQ helicase that participates in homologous recombination (HR) repair and is essential for cellular protection against DNA cross-links.
Synonyms: POL4P
Tractability: PROTAC: ubiquitination databases record sites on it.
Target class: Enzyme; Transferase
Gene: Protein-coding gene on chromosome 4 (2,071,918 to 2,242,121, reverse strand). Ensembl gene ENSG00000130997.
Subcellular location: Nucleus
Subcellular location (Human Protein Atlas): Nucleoplasm
Pathways (Reactome):
DNA Repair: Fanconi Anemia Pathway
Gene Ontology:
Molecular function: cyclin binding; DNA polymerase activity; DNA-directed DNA polymerase activity; protein binding; DNA binding; nucleic acid binding
Biological process: double-strand break repair via homologous recombination; interstrand cross-link repair; translesion synthesis; DNA repair; DNA replication; DNA-templated DNA replication
Cellular component: nucleolus; nucleoplasm; nucleus
Genetic constraint (gnomAD): Loss-of-function variants: 71 observed, 84.88 expected, observed/expected ratio (o/e) 0.84, 90% interval 0.69 to 1.02. The upper end of that interval is the gene's LOEUF score, 1.02, which puts it in group 4 of 6, group 1 being the genes least tolerant of losing a copy. Missense variants: 895 observed, 929.29 expected, observed/expected ratio (o/e) 0.96, 90% interval 0.91 to 1.02. Synonymous variants: 330 observed, 346.18 expected, observed/expected ratio (o/e) 0.95, 90% interval 0.87 to 1.04.
Homologues: Orthologues: chimpanzee POLN (98% identical), macaque POLN (94% identical), dog POLN (74% identical), guinea pig POLN (72% identical), mouse Poln (70% identical), rat Haus3 (70% identical), pig POLN (68% identical), rabbit POLN (65% identical), tropical clawed frog poln (44% identical), zebrafish poln (39% identical).
Diseases named in the same sentence as POLN in open-access papers:
POLN is named in the same sentence as 14 diseases in open-access papers, as found by Europe PMC text mining. Sharing a sentence is not in itself a finding about the gene and the disease. The quoted sentences say what the papers report.
microcephaly (2 papers, 2018 to 2021). A congenital or acquired developmental disorder in which the circumference of the head is smaller than normal for the person's age and sex. "We confined the region of susceptibility for microcephaly and seizures to a 330 kb sized region that encompassed seven candidate genes (LETM1, FGFR3, WHSC1, NELFA, C4orf48, NAT8LI, and POLN)." (PMID 29721507, 2018).
breast carcinoma (1 paper, 2018). "Nearly 50% of breast carcinomas have mutations within the POLN gene, suggesting that polymerase ν may be associated with breast cancer." (PMID 29301327, 2018).
Fanconi anemia (1 paper, 2020). Fanconi anemia (FA) is a hereditary DNA repair disorder characterized by progressive pancytopenia with bone marrow failure, variable congenital malformations and predisposition to develop hematological or solid tumors. "The Fanconi anemia pathway genes FANCB, POLN, DCLRE1A, UBA52, and FANCF genes were significantly (p < 0.01, T-test) downregulated after radiation only in FANCA-deficient HIO lines." (PMID 32085439, 2020).
gastric cancer (1 paper, 2022). A primary or metastatic malignant neoplasm involving the stomach. "Taken together, these findings revealed that the radiotherapy or chemotherapy promoted the expression of DNA repair genes (APLF, EID3, EME2, NPAS2 and POLN) of gastric cancer non-stem stem cells to trigger DNA repair, resulting in the biogenesis of GCSCs." (PMID 36153608, 2022).
prostate tumors (1 paper, 2022). "The frequency of POLN-inactivating variants shown as increased in patients with pancreatic tumors compared to controls and has a 6.9-fold increased risk of prostate tumors in the Chinese population." (PMID 36077770, 2022).
testicular cancer (1 paper, 2015). A primary or metastatic malignant neoplasm that affects the testis. "In human cells, POLN is also highly expressed in testis but very weakly expressed in cell lines, even those derived from testicular cancers (1618K, 833K, SuSa, and TERA1)." (PMID 26269593, 2015).
cancer (6 papers, 2010 to 2022). A tumor composed of atypical neoplastic, often pleomorphic cells that invade other tissues. "Besides this, rare and potentially pathogenic variants were identified in the DNA repair gene POLN and other cancer-related genes such as PPARG, CTC1, DCC and ALPK1." (PMID 36077770, 2022). "We note that other SNPs associated with CIN3/cancer included those in the OAS1, OAS2, and POLN genes." (PMID 20084279, 2010). "Instead, the contribution of NPL and POLN to BC predisposition was not supported by the additional screening of cancer cases." (PMID 32906649, 2020). "In the Human Protein Atlas NPL, POLN and RASAL1 showed generally an increased expression in most cancer tissues." (PMID 32906649, 2020).
POLN also shares sentences with these, for which no sentence is quoted: epithelial ovarian cancer (2 papers); anemia (1); convulsion (1); Intellectual disability (1); ovarian cancer (1); prostate carcinoma (1); tumor (1).